CDY2B (chromodomain Y-linked 2B)
Description:
May have histone acetyltransferase activity.
Synonyms: CDY
Tractability: Small molecule: it has a high-quality binding pocket.
Gene: Protein-coding gene on chromosome Y (17,878,260 to 17,880,220, reverse strand). Ensembl gene ENSG00000129873.
Subcellular location: Nucleus
Gene Ontology:
Molecular function: histone H3K27me3 reader activity; histone H3K9me2/3 reader activity; transcription corepressor activity; protein-lysine-acetyltransferase activity
Biological process: negative regulation of peptidyl-lysine crotonylation; spermatogenesis; chromatin organization; negative regulation of DNA-templated transcription
Cellular component: nucleus
Homologues: Orthologues: macaque CDY (83% identical), mouse Cdyl (61% identical), zebrafish cdyl (47% identical), rat AABR07039112.1 (40% identical), Caenorhabditis elegans B0272.4 (13% identical), Drosophila melanogaster Dci (12% identical), Drosophila melanogaster CG8778 (10% identical), Drosophila melanogaster Srlp (10% identical), Caenorhabditis elegans ech-5 (10% identical), Drosophila melanogaster CG14787 (9% identical), Caenorhabditis elegans ech-3 (9% identical), Drosophila melanogaster HIPP1 (9% identical), and 1 more. Paralogues in human: CDY2A (100% identical), CDY1B (98% identical), CDY1 (96% identical), CDYL (62% identical), CDYL2 (38% identical), ECHS1 (14% identical), ECHDC2 (12% identical), ECHDC3 (12% identical), HIBCH (12% identical), ECH1 (12% identical), AUH (11% identical), ECHDC1 (10% identical), and 1 more.
Diseases named in the same sentence as CDY2B in open-access papers:
CDY2B is named in the same sentence as 1 disease in open-access papers, as found by Europe PMC text mining. Sharing a sentence is not in itself a finding about the gene and the disease.
CDY2B shares sentences with these, for which no sentence is quoted: Azoospermia (1 paper).